TEX261 (testis expressed 261)
Synonyms: MGC32043; TEG-261
Tractability: Antibody: UniProt predicts a signal peptide or a membrane-spanning region. PROTAC: ubiquitination databases record sites on it.
Gene: Protein-coding gene on chromosome 2 (70,968,325 to 70,994,873, reverse strand). Ensembl gene ENSG00000144043.
Subcellular location: Membrane
Subcellular location (Human Protein Atlas): Nucleoplasm; Cytosol
Gene Ontology:
Molecular function: COPII receptor activity
Biological process: endoplasmic reticulum to Golgi vesicle-mediated transport
Cellular component: COPII-coated ER to Golgi transport vesicle; endoplasmic reticulum membrane; Golgi membrane; membrane
Genetic constraint (gnomAD): Loss-of-function variants: 10 observed, 19.32 expected, observed/expected ratio (o/e) 0.52, 90% interval 0.32 to 0.88. The upper end of that interval is the gene's LOEUF score, 0.88, which puts it in group 3 of 6, group 1 being the genes least tolerant of losing a copy. Missense variants: 188 observed, 223.66 expected, observed/expected ratio (o/e) 0.84, 90% interval 0.75 to 0.95. Synonymous variants: 84 observed, 91.42 expected, observed/expected ratio (o/e) 0.92, 90% interval 0.77 to 1.1.
Homologues: Orthologues: chimpanzee TEX261 (100% identical), mouse Tex261 (99% identical), rat Tex261 (99% identical), dog TEX261 (99% identical), pig TEX261 (99% identical), guinea pig TEX261 (98% identical), tropical clawed frog tex261 (90% identical), zebrafish tex261 (86% identical), rabbit TEX261 (82% identical), macaque TEX261 (60% identical), Drosophila melanogaster CG3500 (50% identical).
Diseases named in the same sentence as TEX261 in open-access papers:
TEX261 is named in the same sentence as 4 diseases in open-access papers, as found by Europe PMC text mining. Sharing a sentence is not in itself a finding about the gene and the disease. The quoted sentences say what the papers report.
endometrial cancer (1 paper, 2024). Primary or metastatic malignant neoplasm involving the endometrium (mucous membrane that lines the endometrial cavity). "Similarly, The Human Protein Atlas database have alluded that TEX261 is a prognostic marker in liver and endometrial cancer, with unfavourable outcome." (PMID 38268823, 2024).
prostate carcinoma (1 paper, 2022). A carcinoma that arises from epithelial cells of the prostate gland. "Tex261, as a target of miR-28-5p in prostate cancer, affects cell proliferation, survival and apoptosis." (PMID 36408272, 2022).
sarcopenia (1 paper, 2021). Progressive decline in muscle mass due to aging which results in decreased functional capacity of muscles. "The expression of TEX261 reduced significantly in the sarcopenia of HSS and JSS, but not in that of SSS." (PMID 34704369, 2021).
tumor (1 paper, 2021). "The genes that appeared most frequently among the top projected targets for the 15 patient tumor samples were SLC24A1, ARTN, DHRSX, TEX261, and FRMD8." (PMID 34662337, 2021).